VCP (valosin containing protein)
Diseases named in the same sentence as VCP in open-access papers (continued):
Sharing a sentence is not in itself a finding about the gene and the disease.
tumor (continued). "An orally bioavailable VCP inhibitor, CB-5083, is currently in Phase I clinical trials because it shows therapeutic effects in multiple tumor xenograft models." (PMID 29367883, 2017). "Overall, encapsulation of potent VCP-inhibitor DBeQ into a dendrimer allows selective VCP-mediated proteostasis-inhibition for controlling NSCLC-tumor growth and progression to allow tumor-targeted sustained drug delivery." (PMID 27434122, 2016). "In summary, these results indicate that DDNDBeQ has the potential to provide sustained drug delivery to tumor cells by selectively inhibiting VCP mediated proteostasis." (PMID 27434122, 2016). "Although many VCP inhibitors are available, most of these therapeutic compounds have low specificity for targeted tumor cell delivery." (PMID 27434122, 2016). "The tumor volume, number of nodules, and the incidence of lung metastasis were drastically decreased in VCP knockdown HCT116 cells." (PMID 27344168, 2016). "In conclusion, our present data verifies the vital role of VCP in cell cycle progression of H1299 cells verifying its crucial function in promoting tumor growth." (PMID 27434122, 2016). "Our data highlights the potential of DDNDBeQ in providing tumor-targeted delivery of VCP inhibitor(s) to control NSCLC growth, progression and metastasis." (PMID 27434122, 2016). "Compared with NC transfectants, cells transfected with si-VCP revealed a delayed tumor formation time (11/15 versus 0/15 on day 10) and a significant reduction in the tumor size." (PMID 22536440, 2012). "Although it has been reported that VCP expression level is diverse in the different tumor samples and has prognostic significance for disease-free and overall survival of patients with HCC, the role of VCP in HCC is unclear." (PMID 22536440, 2012). "We also identified the critical role of elevated VCP expression in promoting tumor growth using the in vitro tumor growth model." (PMID 22216170, 2011). "Our data demonstrates the critical role of VCP in regulating tumor cell cycle, suggesting its involvement in NSCLC progression and invasion." (PMID 22216170, 2011). "Our data suggest that VCP regulates a number of critical cellular processes involved in NSCLC tumor development, growth and metastasis." (PMID 22216170, 2011). "Whereas VCP/p97 was observed predominantly in the cytosol of U937 tumor and retrodifferentiated cells, a significant nuclear accumulation appeared during differentiation and G0/G1 growth arrest." (PMID 18279508, 2008). "While LPCAT1, AIFM2, and VCP have not been directly validated as diagnostic biomarkers, they are functionally implicated in tumor pathogenesis." (PMID 40804485, 2025). "Furthermore, the inhibition of VCP/p97 is known to induce immunogenic cell death (ICD) in tumor cells." (PMID 41357812, 2025). "Importantly, we validated the presence of VCP in tumor-derived sEV through western blot analysis, suggesting a potential mechanism for its delivery to endothelial cells." (PMID 39802400, 2025). "Thus, this study facilitates to dissect the mechanism of Ter94/VCP inhibitors inhibiting tumor progression and provides guidance for their clinical application." (PMID 38710747, 2024). "IPTG-induced AT3 or VCP depletion blocked tumor growth in xenografted FU-UR-1 cells in NRG mice." (PMID 38326311, 2024). "In the further, it is necessary to explore whether Ter94/VCP inhibitors exert anti-tumor effects by activating the Hippo pathway." (PMID 38710747, 2024).
tumor (continued). "Moreover, the elevated VCP expression promoted tumor growth in nude mice models bearing subcutaneous HCC." (PMID 35562734, 2022). "In addition, in the subcutaneous tumor and lung metastasis mouse model, VCP knockdown in HCT116 cells suppressed carcinogenesis and metastasis in vivo." (PMID 27344168, 2016). "Hence, we utilized here a dendrimer-encapsulation of a potent VCP inhibitor drug, DBeQ, in order to circumvent this problem and allow tumor-specific targeting by using a sustained and targeted drug release system." (PMID 27434122, 2016). "Furthermore, in a subcutaneous mouse tumor model, VCP knockdown significantly reduced subcutaneous tumor growth, and VCP over-expression promoted subcutaneous tumor growth." (PMID 27344168, 2016). "All these findings indicate that VCP can be used as a potential marker of tumor." (PMID 22536440, 2012). "The in vivo study showed that enhancing the level of miR-129-5p could suppress the growth of tumor, which was similar to si-VCP group." (PMID 22536440, 2012). "Cells transfected with miR-129-5p revealed a delayed tumor formation time (11/15 versus 2/15 on day 10) and a significant reduction in the tumor size, which was consist with the result of si-VCP group, suggesting a potential tumor suppressive effect of miR-129-5p." (PMID 22536440, 2012). "In addition, the immunohistochemical analysis showed that the level of VCP in the tumor from si-VCP group was lower than that from NC group." (PMID 22536440, 2012). "Suppression of the expression of VCP or increasing the level of miR-129-5p could induce cell apoptosis and migration in vitro and inhibit the tumor genesis of HCC in vivo." (PMID 22536440, 2012). "VCP has been shown to regulate NFκB suggesting its role in tumor metastasis." (PMID 22216170, 2011). "In addition to proliferation and apoptosis, we found that VCP also mediates tumor cell migration and invasion suggesting its critical role in NSCLC pathogenesis and progression." (PMID 22216170, 2011). "Moreover, we found that VCP inhibition by small molecule significantly (p<0.05) reduced NSCLC tumor growth in both in vitro and in vivo models." (PMID 22216170, 2011). "Our results support that C1QL1 can act as a tumor suppressor of BrCa by modulating the C1QL1/HSP90α/VCP-ERS/UPR pathway, implying that the promoter methylation status of C1QL1 or the expression of C1QL1 may represent a potential marker for the diagnosis or prognosis of BrCa." (PMID 40583061, 2025). "Moreover, VCP had higher levels in tumor tissue lysates than lysates of normal tissues." (PMID 40507244, 2025). "Indeed, treatment of mice harboring Hepa1-6 tumors with the specific VCP inhibitor CB-5083 combined with anti-PD1 suppressed tumor growth without mouse weight loss compared to monotherapy or control groups." (PMID 39848960, 2025). "Moreover, we used LGA-PEI (LPNP) nanoparticles to effectively administer miR-198 to tumors in vivo, inducing tumor sensitization to gemcitabine and leading to a significant reduction in tumor burden and metastases and a concomitant downregulation of VCP expression and autophagy maturation." (PMID 37631252, 2023). "The expression of NPL4,UFD1,VCP were higher in paired tumor than adjacent normal tissues(p< 0.001).Furthermore, lower expression of NPL4 and UFD1 were significantly associated with a longer OS prognosis when VCP expression could not cause a significant OS difference." (PMID 35290151, 2022). "Moreover, the proposed strategy has a potential for potent tumor-targeted VCP-inhibition." (PMID 27434122, 2016). "Inhibition of VCP could suppress HCC tumor progression in nude mice." (PMID 22536440, 2012). "In addition, down-regulation of VCP with siRNAs could dramatically suppress the genesis and progression of tumor in vivo." (PMID 22536440, 2012). "In addition, VCP/p97 may increase the metastatic potential in tumor entities, possibly by controlling the stability of IκBα, an inhibitor of NFκB." (PMID 18279508, 2008).
tumor (continued). "Pharmacological or genetic inhibition of VCP reduced mouse PNF cell-derived sphere number, and genetic inhibition of Vcp in Schwann cell precursors decreased tumor-like lesion numbers in a cell transplantation model." (PMID 42121950, 2026). "The analysis of LSIL and HSIL tissues, as well as SCC tumor samples of grades G1–3, revealed distinct expression patterns for the four proteins (TOP2A, MCM2, VCP, and p16INK4a)." (PMID 40507244, 2025). "We demonstrate that hCMEC/D3 cells treated with tumor EVs carrying Valosin-Containing Protein (VCP) have a distinct VEGFR2 phosphorylation, while VCP modulation in hCMEC/D3 cells by transfection resulted in changes in barrier properties." (PMID 39802400, 2025). "In CRC, valosin-containing protein (VCP) upregulates CPT1 expression by accelerating HDAC1 degradation to enhance FAO and tumor progression, while CPT1A-mediated FAO suppresses anoikis to facilitate metastasis." (PMID 41488637, 2025). "Despite these limitations, we focused on VCP’s role in the HCC tumor microenvironment, exploring how it suppresses CD8+T cells function via downstream metabolites, particularly G3P, which links tumor metabolism with immune dysfunction." (PMID 39848960, 2025). "To further investigate the mechanism of VCP’s effect, we isolated CD8+T cells and cultured them in conditioned medium (CM), which was derived from a 24-h incubation of tumor cells." (PMID 39848960, 2025). "The interaction of MTDH with IRE1α and its destabilization by VCP offers an interesting view on tumor control by functionally interacting MTDH, IRE1α, and VCP." (PMID 38727283, 2024). "Immunohistochemistry also identified significant nuclear VCP in both mouse and human ASPS tumor tissue microarrays." (PMID 38326311, 2024). "VCP was overexpressed in NSCLC tumor B cells, NSCLC PBLs, and tumor T cells, as well as a C4 /C9-CTLA CD4 T cell cluster." (PMID 35804895, 2022). "In vivo and in vitro studies showed that it bound to the D2 domain, inhibited VCP with moderate oral bioavailability, rapidly induced the UPR, induced apoptosis and inhibited tumor growth in hematological xenograft models." (PMID 34576340, 2021). "Furthermore, CQ could inhibit tumor growth saved by VCP overexpression." (PMID 33758608, 2021). "The tumor volume, number of nodules, and the incidence of lung metastasis were significantly increased in RKO cells which were transfected with lenti-VCP." (PMID 27344168, 2016). "We designed this study to not only verify the elevated VCP protein expression in adeno- and squamous- NSCLC but also identify if it is involved in tumor pathogenesis and progression." (PMID 22216170, 2011). "Our findings suggested that VCP regulates NSCLC proliferation and apoptosis and indicate its critical role in regulating the tumor cell cycle." (PMID 22216170, 2011). "Our data demonstrate that VCP inhibition controls NSCLC proliferation and progression by regulating tumor cell growth, migration, and apoptosis." (PMID 22216170, 2011). "The mice were treated with functional inhibitor of VCP, EerI (10 μM or DMSO vehicle control) at indicated times on the scale and tumor volume was monitored every week (n = 5)." (PMID 22216170, 2011). "Our results demonstrate the critical role of VCP in promoting NSCLC migration and invasion, implicating VCP in tumor metastasis." (PMID 22216170, 2011). "Importantly, we demonstrated that targeting VCP in combination with anti-PD1 therapy significantly suppresses HCC tumor growth and restores the anti-tumor function of CD8+T cells, suggesting synergistic therapeutic potential." (PMID 39848960, 2025). "Future studies should explore the broader implications of VCP inhibition, including its effects on non-T cell populations and other components of the tumor microenvironment." (PMID 39848960, 2025).
tumor (continued). "Spatial transcriptome mapping of tumor tissue from clinical patients indicated reduced CD8+T cell infiltration in regions exhibiting high VCP expression, contrasting with increased infiltration in regions with low VCP expression." (PMID 39848960, 2025). "In LSCC VCP/p97 expression does not appear to be decisively involved in tumor invasion or metastasis development." (PMID 41357812, 2025). "Yan’s team also proved that the combination of PKA inhibitor and VCP inhibitor and M1 virus reduced the production of virus-induced PD-L1 + DC, MDSC, TAM and T-reg, thereby reduced tumor burden and improved the survival rate of mice, and eventually enhanced the oncolytic effect of M1 virus." (PMID 35401439, 2022). "Overall, these data suggest that the overexpression of VCP may serve as a poor prognostic factor in HCC and promotes tumor progression." (PMID 35562734, 2022). "Consistently, in the current study, we found a remarkable increase in VCP expression in tumor tissues compared to adjacent non-tumorous samples." (PMID 35562734, 2022). "Thus, the DDNDBeQ formulation provides significant benefits over unconjugated VCP inhibitor drugs, to control NSCLC progression and has the potential for further development to allow tumor-targeted sustained drug delivery." (PMID 27434122, 2016). "Another issue is that many of the potent VCP inhibitor drugs are not water soluble, and lack adequate specificity for tumor-targeted proteostasis-inhibition." (PMID 27434122, 2016). "Until now, there are no definitive reports to clarify if VCP is involved in the progression of tumor." (PMID 22536440, 2012). "Finally, we evaluated the therapeutic potential of VCP inhibition and observed significantly reduced NSCLC tumor growth in both in vitro and xenograft murine (athymic-nude) models after EerI treatment (p<0.05)." (PMID 22216170, 2011). "In RMS, both the HSP70 (heat shock 70 kDa protein) inhibitor MAL3-101 and the p97 (valosin containing protein) ATPase inhibitor CB-5083 trigger robust UPR activation, marked by increased eIF2α phosphorylation, ATF4 and CHOP upregulation, and XBP1 splicing, thereby promoting tumor cell death." (PMID 41228282, 2025). "Similarly, Vcp depletion in tumor cells increased tumor cells apoptosis, reduced apoptosis of CD8+T cells, promoted proliferation of CD8+T cells, as well as cytokines expression, which ruled out the impact of VCP on tumor antigen presentation." (PMID 39848960, 2025). "Hematoxylin and eosin (H&E) staining identified an increase in tumor cells in the VCP-overexpressing group, while the immunohistochemical (IHC) analysis showed that in the VCP gene activation group, the expression of FASN, VCP, and USP2 in tumor cells was relatively increased." (PMID 39489738, 2024). "Observations that GCN2 may promote tumour growth or induce apoptosis under conditions of metabolic stress and nutrient deprivation led us to investigate the role of GCN2 in cells challenged by VCP/p97 inhibition." (PMID 30626938, 2019). "Thus, selectively inhibiting VCP’s functions can be developed as potent therapeutic strategy to control NSCLC growth and metastasis, which warrants further standardization in pre-clinical murine models to ensure tumor specific drug delivery." (PMID 27434122, 2016). "Furthermore, the specificity of VCP with regards to the detection of neoplastic vs non-neoplastic disease will need to be assessed before its usefulness as a tumor marker can be definitively established." (PMID 22870330, 2012). "Based on the dual therapeutic potential of VCP inhibition as well as its ability to regulate critical oncogene and tumor suppressor protein levels, we are currently evaluating its therapeutic efficacy in controlling NSCLC metastasis using an intrapulmonary tumor implantation murine model." (PMID 22216170, 2011).
tumor (continued). "Consequently, by evaluating SELENOS and VCP/p97 in TNBC cell lines, tumor tissues, and the TCGA dataset, we evidenced their correlated expression, suggesting that both proteins might represent novel potential prognostic biomarkers and/or therapeutic targets in TNBC." (PMID 35158912, 2022).
myopathy (41 papers, 2010 to 2025). A disease of the muscle in which the muscle fibers do not function properly. "Pathogenic variants in the gene encoding VCP cause multisystem proteinopathies (MSPs), a set of genetic diseases characterized by myopathy, bone disease and/or neurodegeneration of central and/or peripheral nervous systems." (PMID 38891822, 2024). "Since VCP plays such a profound role in genome stability, perhaps pathogenic VCP causes a reduction in healthy nuclei, contributing to myopathy by reducing fiber size." (PMID 38891822, 2024). "The mouse model containing VCP/p97 mutations recapitulates the clinical manifestation of the myopathy observed in IBMPFD patients." (PMID 37602234, 2023). "Pathogenic VCP/p97 mutations cause a multisystem proteinopathy linked to different pathologies, such as inclusion bodies myopathy associated with Paget’s disease of the bone and FTD (IBMPFD) as well as ALS." (PMID 35694405, 2022). "Most of the phenotypes associated with VCP-MSP have been identified in MSP2 patients (myopathy, FTD, ALS, and PDB)." (PMID 35741724, 2022). "A missense mutation (R93C) in the valosin-containing protein (gene) was also described in a Brazilian family presenting with progressive myopathy together with clinical and cognitive features of FTD." (PMID 34552552, 2021). "Recent mouse models of VCP showed that activation of the NLRP3 inflammasome is associated with VCP protein myopathy." (PMID 32116499, 2020). "Here we present a case with variable phenotypic manifestations ranging from an axonal sensorimotor polyneuropathy to a lower motor neuron syndrome or even a myopathy all arising from a mutation in the gene encoding VCP." (PMID 25878907, 2015). "Moreover, p97/VCP deficiency resulted in the accumulation of numerous vesicular bodies, autophagy impairment, and altered myofibrillar organization, causing a severe myopathy." (PMID 33078210, 2021). "VCP accumulates inside of rimmed vacuoles suggesting that it may have a role in TMD myopathology with similarities to other neurodegenerative proteinopathies such as VCP-mutated myopathy." (PMID 24618559, 2014). "We performed bone scan imaging in twelve patients (6 females, 6 males) with confirmed VCP gene mutation six (50%) of which has myopathy alone, four (33%) with both PDB and myopathy, and two (15%) were presymptomatic carriers." (PMID 38467645, 2024). "For example, a patient with myopathy who is found to have a pathogenic VCP mutation on a multi-gene panel may be referred for electromyography, skeletal survey, and MRI of the head, to identify other features in the clinical spectrum of VCP-MSP prior to the development of symptoms." (PMID 35741724, 2022). "The inactivation of VCP in skeletal muscle of adult mice leads to a necrotic myopathy, preceded by upregulation of LGALS3/Galectin-3, a typical marker of damaged lysosomes, and to the accumulation of autophagic proteins and of damaged lysosomes." (PMID 35273561, 2022). "Four molecular chaperones, glucose-regulated protein 94 (GRP94), glucose-regulated protein 78 (GRP78), calreticulin and calnexin and valosin containing protein (VCP) were highly expressed in GNE myopathy." (PMID 23472144, 2013).